FOXP4 (forkhead box P4)
Diseases named in the same sentence as FOXP4 in open-access papers (continued):
Sharing a sentence is not in itself a finding about the gene and the disease.
tumor (continued). "Moreover, exosomes carrying miR‐101‐3p and miR‐423‐5p suppress tumor cell proliferation, migration, and invasion and enhance cell apoptosis, which could be tumor‐suppressive by targeting the FoxP4 gene." (PMID 37170647, 2023). "Hence, FOXP4 could facilitate tumor metastasis via upregulating Treg cells and diminishing CD8+T cell cytotoxicity." (PMID 36203616, 2022). "When FOXP4-downregulated PPP268 cells were subcutaneously allografted in C57BL/6 N wild-type mice, tumor formation was significantly reduced." (PMID 38890503, 2024). "FOXP4 functions as a transcriptional target of Wnt/β-catenin/TCF4, facilitating PTK7 transcription and thereby fostering OV tumor development and advancement." (PMID 38740744, 2024). "Zhang and Zhang found FoxP4 functioned as a tumor promoter in LIHC cells by transcriptionally regulating Slug and highlighted the potential effects of FoxP4 on the prognosis and treatment of LIHC." (PMID 34337013, 2021). "In essence, FOXP4 emerges as a pivotal transcriptional target within the Wnt/β-catenin/TCF4 signaling axis, regulating the downstream transcription factor PTK7 and thereby fostering tumor proliferation, migration, and invasiveness." (PMID 38740744, 2024). "Overexpression of tumour suppressors, such as EIF3F, FOXP4, ZBTB4, GANAB, TMEM141 was observed." (PMID 33795785, 2021).
cancer (25 papers, 2017 to 2025). A tumor composed of atypical neoplastic, often pleomorphic cells that invade other tissues. "In this study, we delve into the HBV's interaction with the host gene Foxp4, a key player in tumorigenesis and cancer progression." (PMID 39513116, 2024). "Of the genes whose function is related to the Wnt/β-catenin signaling pathway, we focused on PTK7, as it showed the most significant correlation with FOXP4 in OV and most other cancer types in TCGA." (PMID 38740744, 2024). "This study marks a significant contribution to understanding the complex functions of FOXP4 in cancer development." (PMID 39513116, 2024). "Utilizing TCGA and GTEx datasets, we analyzed FOXP4 mRNA expression across 33 human cancers and corresponding normal tissues using the GEPIA tool." (PMID 38740744, 2024). "In the present study, we utilized the human AR-QL (23 Q) construct to overexpress AR and suppress cancer growth through decreasing FOXP4 expression." (PMID 38890503, 2024). "FOXP4 was selectively upregulated in 6 cancer types when compared to their respective normal tissues." (PMID 38740744, 2024). "The Foxp family, which is composed of Foxp1, Foxp2, Fxop3 and Foxp4, is also involved in diverse biological processes including development, immune disorders and cancer progression." (PMID 35974052, 2022). "FOXP4 is a family of forkhead box transcription factors, with a critical role in cancer growth and metastasis in different types of cancer." (PMID 34199293, 2021). "FOXP4, a member of forkhead box family, is expressed in various organizations, and relate to diverse carcinoma progression." (PMID 32436934, 2020). "Foxp4 plays a critical role in tumorigenesis and cancer progression 14-17." (PMID 39513116, 2024). "Additionally, the Forkhead box (FOX) family of transcription factors (FOXF1, FOXS1, FOXM1, FOXK1, FOXP4, and FOXC1) play a role in cell differentiation and proliferation and are implicated in cancer and drug resistance." (PMID 35854219, 2022). "Likewise, forkhead-box P4 (FOXP4) highly contributes to cancer cell growth and invasion, circ-ZNF609 remarkably increases in RCC tissues and consequently promotes the expression of FOXP4 by sponging with miR-138-5p." (PMID 33776764, 2021). "FOXP4 has been reported in human cancers due to its oncogenic property." (PMID 31209207, 2019). "FOXP4, belonging to the FOXP subfamily, plays a pivotal role in various biological processes including cancer, cell cycle regulation, and embryonic development." (PMID 38740744, 2024). "In a number of cancer types, including THCA, we observed that lower FOXP1, FOXP2 and higher FOXP3, FOXP4 levels in cancer tissues when compared with matched normal tissue." (PMID 36203616, 2022). "MiR-3184-5p and miR-181c-3p targets forkhead box P4 (FOXP4), a gene involved in cancer growth and metastasis, and peroxisome proliferator-activated receptor alpha (PPARγ), known to be an oncogene." (PMID 34359591, 2021). "Forkhead box P (FOXP) TFs—FOXP1, FOXP2, FOXP3, and FOXP4—are involved in embryonic development, immune disorders, and cancer progression, but FOXP3’s targeting of CD4 + CD25+ regulatory T (Treg) cells and its dual role as an OCG or tumor suppressor in cancers are unclear and controversial." (PMID 38827026, 2024).
neurodevelopmental disorder (6 papers, 2021 to 2024). A behavioral and cognitive disorder with onset during the developmental period that involves impaired or aberrant development of intellectual, motor, or social functions. "Moreover, mutations in the FOXP4 gene are associated with neurodevelopmental disorders, providing further support for the potential influence of FOXP4 in neurologic LC." (PMID 40046430, 2024). "These transcription factors, including FOXP4, are associated with neurodevelopmental disorders." (PMID 36107978, 2022). "More thorough phenotypic comparison studies between these distinct neurodevelopmental disorders and functional follow‐up would be required to uncover whether equivalent variants in FOXP1 and FOXP4 directly impact speech and language or whether they have an indirect effect on the function of FOXP2." (PMID 34260143, 2021).
infection (5 papers, 2012 to 2025). The state of being infected such as from the introduction of a foreign agent such as serum, vaccine, antigenic substance or organism. "Mice with Foxp4 deficient T cells control infection with T. gondii and lymphocytic choriomeningits virus (LCMV)." (PMID 22912696, 2012). "To more thoroughly evaluate effector function, we examined Foxp4 deficient T cell responses following pathogenic infection." (PMID 22912696, 2012). "In Foxp4 cKO mice, the reduced IFNγ production in response to STAg forty days post-infection may be caused by defects in CD4 T cell help." (PMID 22912696, 2012). "We next asked whether T cell specific Foxp4 deficiency alters the physiologic response to pathogenic infection." (PMID 22912696, 2012). "We found that two variants were nominally associated with the risk of severe disease among cases (rs11919389 near RPL24, P = 0.029 and rs1886814 near FOXP4, P = 0.018), suggesting that these loci also modulate disease severity after infection with SARS-CoV-2." (PMID 35241825, 2022). "Following chronic infection with T. gondii, Foxp4 cKO mice controlled the infection similarly to controls as evidenced by similar numbers of cysts and quantitatively equal parasite burden." (PMID 22912696, 2012). "FOXP4 is a transcription factor expressed in both thymocytes and peripheral CD4+ and CD8+ T cells, and is necessary for normal T cell cytokine recall responses to antigen following pathogenic infection." (PMID 36531218, 2022). "We conclude that Foxp4 is dispensable for T cell development, but necessary for normal T cell cytokine recall responses to antigen following pathogenic infection." (PMID 22912696, 2012). "FOXP4 expression was the highest in type 2 alveolar cells in individuals without SARS-CoV-2 infection and during active infection, suggesting that SARS-CoV-2 infection was not required for FOXP4 expression." (PMID 40399555, 2025). "If Foxp4 regulates CD4 T cell help, we would expect more impaired CD8 responses at later points post-infection, leading to uncontrolled infection and increased mortality, which was not evident in our shorter infection." (PMID 22912696, 2012).
FOXP4 also shares sentences with these, for which no sentence is quoted: colorectal cancer (3 papers); emphysema (2); immune disorders (2); kidney tumors (2); pancreatic cancer (2); airway hyperresponsiveness (1); autoimmune disease (1); B cell lymphomas (1); Bardet-Biedl syndrome (1); bladder cancer (1); bone cancer (1); cardiovascular disease (1); cryptorchidism (1); Duane retraction syndrome (1); endometriosis (1); Flavivirus Infections (1); gastric cancer (1); glioblastoma (1); inflammatory bowel disease (1); interstitial lung disease (1); larynx carcinoma (1); metastatic prostate carcinoma (1); papillary thyroid cancer (1); renal cell carcinoma (1); respiratory failure (1); sensorineural hearing loss (1); type 1 diabetes mellitus (1); ventricular septal defect (1).